NUP88 (nucleoporin 88)
Description:
Component of nuclear pore complex.
Synonyms: MGC8530; FADS4
Tractability: PROTAC: ubiquitination databases record sites on it; its protein half-life has been measured.
Gene: Protein-coding gene on chromosome 17 (5,359,668 to 5,420,164, reverse strand). Ensembl gene ENSG00000108559.
Subcellular location: Nucleus, nuclear pore complex
Subcellular location (Human Protein Atlas): Nucleoplasm
Pathways (Reactome):
Disease: Defective TPR may confer susceptibility towards thyroid papillary carcinoma (TPC); HCMV Early Events; HCMV Late Events; NEP/NS2 Interacts with the Cellular Export Machinery; NS1 Mediated Effects on Host Pathways; Nuclear import of Rev protein; Rev-mediated nuclear export of HIV RNA; SARS-CoV-2 activates/modulates innate and adaptive immune responses; Transport of Ribonucleoproteins into the Host Nucleus; Viral Messenger RNA Synthesis; Vpr-mediated nuclear import of PICs
Metabolism of RNA: Transport of Mature mRNA Derived from an Intronless Transcript; Transport of Mature mRNA derived from an Intron-Containing Transcript; Transport of the SLBP Dependant Mature mRNA; Transport of the SLBP independent Mature mRNA; snRNP Assembly; tRNA processing in the nucleus
Metabolism of proteins: SUMOylation of DNA damage response and repair proteins; SUMOylation of DNA replication proteins; SUMOylation of RNA binding proteins; SUMOylation of SUMOylation proteins; SUMOylation of chromatin organization proteins; SUMOylation of ubiquitinylation proteins
Metabolism: IP3 and IP4 transport between cytosol and nucleus; IP6 and IP7 transport between cytosol and nucleus; IPs transport between nucleus and cytosol; Regulation of Glucokinase by Glucokinase Regulatory Protein
Cell Cycle: Nuclear Pore Complex (NPC) Disassembly
Cellular responses to stimuli: Regulation of HSF1-mediated heat shock response
Immune System: ISG15 antiviral mechanism
Gene Ontology:
Molecular function: protein binding; structural constituent of nuclear pore
Biological process: mRNA export from nucleus; nucleocytoplasmic transport; protein import into nucleus; ribosomal large subunit export from nucleus; ribosomal small subunit export from nucleus
Cellular component: nuclear envelope; nuclear pore; cytosol
Genetic constraint (gnomAD): Loss-of-function variants: 42 observed, 72.68 expected, observed/expected ratio (o/e) 0.58, 90% interval 0.45 to 0.75. The upper end of that interval is the gene's LOEUF score, 0.75, which puts it in group 3 of 6, group 1 being the genes least tolerant of losing a copy. Missense variants: 756 observed, 781.42 expected, observed/expected ratio (o/e) 0.97, 90% interval 0.91 to 1.03. Synonymous variants: 296 observed, 300.21 expected, observed/expected ratio (o/e) 0.99, 90% interval 0.9 to 1.09.
Homologues: Orthologues: chimpanzee NUP88 (99% identical), macaque NUP88 (97% identical), pig NUP88 (92% identical), rabbit NUP88 (91% identical), guinea pig NUP88 (90% identical), mouse Nup88 (90% identical), rat Nup88 (87% identical), dog NUP88 (83% identical), tropical clawed frog nup88 (64% identical), zebrafish nup88 (63% identical), Drosophila melanogaster mbo (26% identical).